FASN (fatty acid synthase)
Description:
Fatty acid synthetase is a multifunctional enzyme that catalyzes the de novo biosynthesis of long-chain saturated fatty acids starting from acetyl-CoA and malonyl-CoA in the presence of NADPH. This multifunctional protein contains 7 catalytic activities and a site for the binding of the prosthetic group 4'-phosphopantetheine of the acyl carrier protein ([ACP]) domain. (Microbial infection) Fatty acid synthetase activity is required for SARS coronavirus-2/SARS-CoV-2 replication.
Synonyms: FAS; SDR27X1; OA-519
Tractability: Small molecule: a structure with a bound ligand is known; a high-quality ligand is known; it has a high-quality binding pocket; it belongs to a druggable protein family. Antibody: its Gene Ontology location is reachable by antibodies, with high confidence; the Human Protein Atlas places it where antibodies can reach. PROTAC: UniProt records ubiquitination sites on it; ubiquitination databases record sites on it; its protein half-life has been measured; a small molecule that binds it is known.
Target class: Enzyme; Transferase
Chemical probes: BI 99179 (high quality), GSK2194069 (high quality), ML356, PD134316
Safety:
Unwanted effects reported when the protein is acted on. In parentheses: how it was acted on, where the effect was seen, and who reports it.
Increased, Liver Steatosis (activation; source: AOP-Wiki)
N/A, Liver Steatosis (activation; source: AOP-Wiki)
Gene: Protein-coding gene on chromosome 17 (82,078,338 to 82,098,294, reverse strand). Ensembl gene ENSG00000169710.
Subcellular location: Cytoplasm; Melanosome
Subcellular location (Human Protein Atlas): Cytosol; Plasma membrane
Pathways (Reactome):
Metabolism: Activation of gene expression by SREBF (SREBP); ChREBP activates metabolic gene expression; Fatty acyl-CoA biosynthesis; Vitamin B5 (pantothenate) metabolism
Disease: Dengue Virus Genome Translation and Replication; Dengue Virus-Host Interactions
Signal Transduction: NR1H2 & NR1H3 regulate gene expression linked to lipogenesis
Gene Ontology:
Molecular function: (3R)-hydroxyacyl-[acyl-carrier-protein] dehydratase activity; 3-oxoacyl-[acyl-carrier-protein] reductase (NADPH) activity; 3-oxoacyl-[acyl-carrier-protein] synthase activity; [acyl-carrier-protein] S-acetyltransferase activity; cadherin binding; enoyl-[acyl-carrier-protein] reductase (NADPH) activity; fatty acid synthase activity; protein binding; RNA binding; [acyl-carrier-protein] S-malonyltransferase activity; acyltransferase activity; fatty acyl-[ACP] hydrolase activity; identical protein binding; oxidoreductase activity; phosphopantetheine binding; transferase activity
Biological process: fatty acid metabolic process; host-mediated perturbation of viral process; osteoblast differentiation; fatty acid biosynthetic process; fatty-acyl-CoA biosynthetic process; acetyl-CoA metabolic process; lipid biosynthetic process; response to nutrient; response to nutrient levels
Cellular component: cytoplasm; cytosol; extracellular exosome; fatty acid synthase complex; membrane; plasma membrane; melanosome
Genetic constraint (gnomAD): Loss-of-function variants: 50 observed, 223.23 expected, observed/expected ratio (o/e) 0.22, 90% interval 0.18 to 0.28. The synonymous counts are far from expectation, so gnomAD's model fits this gene poorly and the ratio says little. Missense variants: 3,031 observed, 3,342.5 expected, observed/expected ratio (o/e) 0.91, 90% interval 0.88 to 0.93. Synonymous variants: 1,909 observed, 1,521.4 expected, observed/expected ratio (o/e) 1.25, 90% interval 1.21 to 1.3.
Homologues: Orthologues: chimpanzee FASN (99% identical), macaque FASN (93% identical), rat Fasn (82% identical), dog FASN (81% identical), mouse Fasn (81% identical), guinea pig FASN (80% identical), pig FASN (78% identical), zebrafish fasn (64% identical), tropical clawed frog fasn (63% identical), Drosophila melanogaster FASN1 (43% identical), Drosophila melanogaster FASN2 (42% identical), Caenorhabditis elegans F32H2.6 (2% identical). Paralogues in human: OXSM (4% identical).
Diseases named in the same sentence as FASN in open-access papers:
FASN is named in the same sentence as 328 diseases in open-access papers, as found by Europe PMC text mining. Sharing a sentence is not in itself a finding about the gene and the disease. The quoted sentences say what the papers report.
breast cancer (373 papers, 2001 to 2026). A primary or metastatic malignant neoplasm involving the breast. "Previous studies revealed that FASN inhibition causes MtMP disruption and ROS burst in cancer cells, including breast cancer, melanoma, and neuroblastoma." (PMID 40133683, 2025). "Previous studies have linked the cytotoxic sensitivity of breast cancer cells to classical FASN inhibitors like cerulenin and C75 with basal FASN expression levels." (PMID 40733158, 2025). "In breast cancer, FASN overexpression is closely associated with tumor cell proliferation, invasion, and poor prognosis." (PMID 40901481, 2025). "In the context of HER2+ breast cancer, FASN is known as a hallmark feature observed early in most human carcinomas and precursor lesions which has been associated with adverse patient outcomes and therapeutic resistance." (PMID 39934114, 2025). "FASN is a long-studied lipid metabolism target as it is universally increased in breast carcinoma cells and linked to worse prognosis." (PMID 40055794, 2025). "Subsequently, it was discovered that a highly expressed gene in breast cancer encodes fatty acid synthase (FASN), a key enzyme in lipid metabolism." (PMID 38673837, 2024). "Up‐regulation of FASN expression has been found to be associated with cancer progression in several cancer types, such as prostate cancer, ovarian cancer, breast cancer and liver cancer." (PMID 39524139, 2024). "Overexpression of FASN, a key enzyme involved in de novo adipogenesis, was observed in breast cancer tissues and was associated with cancer progression, recurrence, poor prognosis, and pathological findings." (PMID 39333940, 2024). "FASN inhibition has also been associated with reduced glucose uptake and lactate production in breast cancer." (PMID 38425123, 2024). "Recent reports indicate that activated fatty acid metabolism by FASN is associated with reduced immune infiltration in male breast cancer, leading to the promotion of metastasis." (PMID 38060103, 2023). "In the present study, five studies were used for the meta-analysis of 855 patients with breast cancer to examine the association of FASN expression with the clinicopathological characteristics and prognosis." (PMID 37124526, 2023). "FASN (fatty acid synthase) was highly expressed in colon cancer, breast cancer, and renal cell carcinoma and was associated with poor prognosis, tumor recurrence, and drug resistance." (PMID 36703911, 2023). "For instance, it has been demonstrated that FASN is substantially expressed in breast cancer-associated brain metastases, which are detrimental to the prognosis." (PMID 37124526, 2023). "Fatty acid synthase (FASN) expression is associated with a more aggressive breast cancer phenotype and is regulated downstream of receptor tyrosine kinase (RTK) signaling pathways." (PMID 36096767, 2022). "For example, AMPK activation also contributed to SREBP-1 and FASN suppressive effects of adiponectin in breast cancer cells, signifying that APMK is also implicated in the modulation of fatty acid metabolism by adiponectin." (PMID 34986886, 2022). "Inhibition of fatty acid synthase (FASN) stimulates oxidative stress to cause antiproliferation of breast cancer cells." (PMID 35624775, 2022). "Here, we evaluated the putative role of the lipogenic enzyme fatty acid synthase (FASN) as a major cause of HRG-driven endocrine resistance in ER+/HER2-negative breast cancer cells." (PMID 33081219, 2020). "We interrogated transcriptional data from the METABRIC to explore the association between FASN and PR in breast cancer." (PMID 33335078, 2020). "Further studies have found that the use of FASN drug inhibitors can cause breast cancer cells to undergo apoptosis or tumor cell shrinkage, which indicates that FASN has a protective effect on breast cancer cells." (PMID 33096860, 2020).
breast cancer (continued). "The inhibition of FASN in breast cancer cells causes the depletion of the end product long-chain FAs palmitate and the accumulation of the substrate malonyl CoA, which is a potent mediator of cytotoxicity, via the induction of apoptotic cell death." (PMID 31052256, 2019). "Intriguingly these studies pointed out novel functions exerted by LOX-1 as a potent regulator of lipogenesis, regulating FASN expression, and its pro-oncogenic activity in tumors suggesting a link between obesity and susceptibility to breast cancer." (PMID 30718451, 2019). "It has been associated with clinically more aggressive cancers; in stage I breast cancer, there was a four-fold increase in mortality risk associated with the expression of fatty acid synthase in two studies." (PMID 30717356, 2019). "As evident from several studies, the increased activity of FASN in various human cancers, including breast cancer is associated with the progression of the malignant phenotype." (PMID 31030489, 2019). "FASN overexpression is associated with malignant tumors, including breast cancer, prostate cancer, colorectal cancer, gastric cancer, and lung cancer, as well as poor prognosis." (PMID 30237984, 2018). "Previous studies have shown a strong correlation between FASN and the aggressiveness of breast cancer, and increased levels are associated with poor prognosis." (PMID 28650989, 2017). "We present evidence herein that the aberrant lipogenic activity of tumor-associated FASN regulates the response of breast cancer cells to E2-stimulated ERα signaling." (PMID 28240737, 2017). "An increase in phospholipid synthesis is associated with lipogenic enzymes including fatty acid synthase and acetyl-CoA carboxylase a, which are commonly upregulated in breast cancer." (PMID 28535818, 2017). "When FASN expression was restored by ectopic expression in breast cancer cells, retarded cell proliferation caused by miR-15a-16-1 was partially rescued." (PMID 27713175, 2016). "In T47D breast cancer cells, PR-A overexpression resulted in loss of adherent properties and insufficient FASN mRNA transcription, supporting our observation of decreased FASN protein levels in BRCA1mut/+ tissues." (PMID 27246982, 2016). "It was novel to observe the physical association of OPG with FASN for the first time in breast cancer cells." (PMID 27270654, 2016). "In this work, we aimed to examine the influence of the metastasis inducer CCN1 on the expression of cancer cell-associated FASN as well as the role of FASN activity on some of the key metastatic features acquired by CCN1-overexpressing breast cancer cells." (PMID 27713913, 2016). "Experimental and clinical studies have shown that the early stages of tumorigenesis in HER2-overexpressing breast cancer cells are associated with increased activation of the FASN-mediated synthesis of palmitic acid, which is often used to form lipid rafts." (PMID 26640797, 2015). "The extrinsic apoptosis pathway, which is triggered by death domains, was described after siRNA silencing of FASN in breast cancer cells caused the accumulation of malonyl-CoA and ceramide." (PMID 24964211, 2014). "Previous reports have shown that inhibition of FASN induces ER-stress and loss of viability in breast cancer cells." (PMID 24280005, 2013). "Because exogenous HER2 overexpression induces upregulation of fatty acid synthase (FASN) in breast cancer cells, the pathway involving the HER2 receptor is generally considered to regulate lipogenic enzymes." (PMID 23613812, 2013). "Inhibiting the enzyme Fatty Acid Synthase (FASN) leads to apoptosis of breast carcinoma cells, and this is linked to human epidermal growth factor receptor 2 (HER2) signaling pathways in models of simultaneous expression of FASN and HER2." (PMID 22177475, 2011). "Conversely, inhibition of fatty acid synthase has been associated with apoptosis of human breast cancer cells and has been suggested as a target for chemoprevention of breast cancer." (PMID 20205934, 2010).
breast cancer (continued). "Novel associations with high-grade PIN include: breast carcinoma fatty acid synthase and cDNA DKFZp434B0335." (PMID 11384102, 2001). "High levels of FASN expression have been linked to increased fatty acid synthesis, which provides the necessary building blocks for membrane synthesis and energy storage, thereby promoting breast cancer cell growth and metastasis." (PMID 40901481, 2025). "The suppression of FASN activity, either through resveratrol treatment or siRNA-mediated gene silencing, was associated with alterations in signaling pathways crucial for the proliferation and survival of breast cancer cells." (PMID 40733158, 2025). "It is also suggested that higher FASN expression may be linked to a worse prognosis for some specific subtypes of breast cancer." (PMID 37124526, 2023). "Moreover, the expression of FASN has been associated with cancer progression and drug resistance in preclinical models of breast cancer development." (PMID 36551752, 2022). "Our hypothesis was supported by previous studies, which reported that exogenous fatty acid supplementation did not prevent irreversible DNA damage and continuous apoptosis caused by cisplatin‐induced downregulation of FASN in MDA‐MB‐231 breast cancer cells." (PMID 35243817, 2022). "A study conducted by Alò and collaborators demonstrated that FASN overexpression is associated with the stage of progression of breast cancer and that FASN expression can be used as a prognostic indicator for disease-free survival and overall disease survival." (PMID 33808259, 2021). "Moreover, a decreased level of palmitic acid, associated with ACC1 and FASN gene silencing, can induce apoptosis in human breast cancer cells." (PMID 33808259, 2021). "To evaluate whether resistance of ER+ breast cancer cells to endocrine therapies could be linked, at least in part, to activation of FASN, we took advantage of an MCF-7 cell line engineered to overexpress HER2 (MCF-7/HER2-18 cells)." (PMID 33800852, 2021). "To evaluate the relevance of PR isoform expression and ratio on the regulatory activity of prolactin for FASN gene expression, we used the PR-A/PR-B-positive (T47Dco) and PR-null (T47D-Y) variants of the estrogen receptor (ER)/PR-positive breast cancer cell line T47D." (PMID 33335078, 2020). "We first evaluated whether HRG overexpression and autocrine transactivation of HER2, independently of HER2 overexpression, might lead to the up-regulation of tumor-associated FASN in an in vitro model of endocrine resistant, luminal B-like breast cancer." (PMID 33081219, 2020). "Here we observed decreased FASN protein abundance under leucine deficiency in breast cancer cells." (PMID 27579768, 2016). "Because an increase in PI uptake can be viewed as a reliable indicator of cell injury severity, our results suggest that pharmacological blockade of FASN activity causes significantly increased amounts of cellular damage in CCN1-overexpressing when compared with CCN1-negative breast cancer cells." (PMID 27713913, 2016). "FASN is also associated with resistance to trastuzumab or adriamycin resistance in breast cancer." (PMID 26437434, 2015). "FASN has been linked to ErbB2-induced breast cancer chemoresistance to docetaxel." (PMID 26437434, 2015). "Thus, HER2 overexpression in breast cancer cells is associated with constitutive upregulation of the endogenous FASN-catalyzed biogenesis of palmitate." (PMID 26640797, 2015). "We hypothesized that FASN may be the downstream effector underlying ER/HER2 crosstalk through the PI3K/AKT/mTOR pathway in ER/HER2-positive breast cancer." (PMID 24866893, 2014). "Also elevated levels of fatty acid synthase (FASN) have been associated with the development of resistance towards doxorubicin in breast cancer cells." (PMID 23613870, 2013). "Thus, FASN overexpression has been associated with poor prognosis in breast cancer patients." (PMID 21080941, 2010).
breast cancer (continued). "Together, these results suggest that FASN-derived TAG is necessary for metastatic breast cancer cell migration." (PMID 40640944, 2025). "FASN is a prominent target for breast cancer therapy, largely due to two distinctive characteristics: tissue distribution and enzymatic activity." (PMID 40002245, 2025). "Our current study demonstrated that resveratrol, as a highly active FASN inhibitor, inhibited both the intracellular FASN activity and FASN expression, and thus induced apoptosis among the three molecular subtypes of breast cancer cell lines." (PMID 40733158, 2025). "In the context of HER2-positive breast cancer, genes including ACLY, FASN, CPT1/2, CD36, and SCD1 have been associated with drug sensitivity to targeted therapies 34,35." (PMID 40303293, 2025). "In vitro investigations have demonstrated a decelerated cell proliferation in HER2-positive breast cancer cells following knockdown of FASN following PPARG overexpression." (PMID 40303293, 2025). "While early-generation FASN inhibitors demonstrated potential efficacy for tumor growth restriction in preclinical breast cancer models, their clinical translation was limited due to substantial toxicity observed in both animal models and human trials." (PMID 40055794, 2025). "In breast cancer, FASN was found to be elevated and essential for tumors metastasizing to the brain, where the microenvironment has low lipid availability in a mouse model." (PMID 40552664, 2025). "We demonstrate that breast cancer cells resistant to endocrine therapies have increased FASN activity, PUFAs with > 6 double bonds, and lipid storage." (PMID 40055794, 2025). "Inhibition of FAK has shown synergistic apoptotic effects with EGF receptor blockade in breast cancer, suggesting that disrupting phospholipid synthesis via FASN inhibition impairs EGFR localization, attenuates FAK-associated signaling, and induces apoptosis." (PMID 40733158, 2025). "Our findings demonstrate that resveratrol not only suppresses FASN expression but also significantly reduces intracellular FASN enzymatic activity in a variety of breast cancer cell lines, highlighting a more universal mechanism of action." (PMID 40733158, 2025). "For instance, in breast cancer preclinical models, FASN inhibitors have been demonstrated to effectively reduce tumor growth and metastasis." (PMID 40901481, 2025). "Of note, several studies have demonstrated that FASN inhibition reduces breast cancer cell survival and migration potentially leading to reduced metastatic capacity." (PMID 40640944, 2025). "S-palmitoylation of PHGDH and FASN promotes chemoresistance in breast cancer, while palmitoylation of ACACA and GPX4 influences lipid metabolic reprogramming and ferroptosis resistance, respectively." (PMID 40626019, 2025). "We further proved that a combination of resveratrol and FASN siRNA treatment decreased the amount of intracellular fatty acid compared with resveratrol treatment alone in breast cancer cells." (PMID 40733158, 2025). "Through the targeted delivery of FASN siRNA, they significantly inhibited FASN expression, thereby suppressing the proliferation of breast cancer cells." (PMID 40137165, 2025). "In a clinical study of TNBC patients, investigators showed higher breast cancer proliferation activity with increased expression of FASN." (PMID 40256431, 2025). "Increased fatty acid synthase (FASN) gene expression in breast cancer cells has been identified as a way to overcome low lipid availability in the brain." (PMID 40076927, 2025). "Genes identified included novel genes such as HPGD, FASN and KRT81, as well as SCIN and TPM1 which have already been confirmed in acquired drug resistance mechanisms associated with HER2-positive breast cancer." (PMID 40946111, 2025). "For instance, FASN has a close relationship with breast cancer metastasized to the brain, making it a potential biomarker for breast cancer brain metastasis." (PMID 40002245, 2025).